TNF (tumor necrosis factor)
Diseases named in the same sentence as TNF in open-access papers (continued):
Sharing a sentence is not in itself a finding about the gene and the disease.
atherosclerosis (continued). "Second, flavonoids in tea can inhibit pro-inflammatory cytokines associated with atherosclerosis (such as IL-6 and TNF-α)." (PMID 40537848, 2025). "These drugs downregulate inflammatory cytokines, such as IL-6 and TNF-α, which are paradoxically implicated in the pathogenesis of both atherosclerosis and mood disorders." (PMID 40932955, 2025). "KEGG enrichment analysis revealed several disease-related pathways, including lipid and atherosclerosis, IL−17 pathway, TNF pathway, NF−κB pathway, Kaposi sarcoma-associated herpesvirus infection, fluid shear stress, and atherosclerosis." (PMID 40365322, 2025). "TNF-a, also known as tumor necrosis factor-alpha, is a crucial risk factor for the development and course of atherosclerosis." (PMID 40218291, 2025). "Elevated TNF-α levels are associated with increased atherosclerosis severity and cardiovascular mortality." (PMID 40217801, 2025). "The elevated TG/HDL-c ratio and smoking both accentuate atherosclerosis and endothelial dysfunction and increase the serum levels of pro-inflammatory cytokines (especially TNF-α), leading to an expanded recurrence risk of IS in the RA population." (PMID 41010664, 2025). "Regular consumption of EVOO, and particularly HP-EVOO, seems to decrease inflammatory markers implicated in the atherosclerosis process such as TNF-α, along with a reduction in ROS, which causes oxidative damage to the heart cells." (PMID 40136590, 2025). "Within the cardiovascular system, increased TNF-α concentrations are linked to vascular inflammation, the development of atherosclerosis, and the progression of heart failure." (PMID 40565222, 2025). "KEGG pathway enrichment analysis further revealed that the hub genes were associated with fluid shear-stress-mediated atherosclerosis, TNF signalling, the HIF-1 signalling pathway, and the HIF-1 signalling pathway." (PMID 40427439, 2025). "This differentiation promotes macrophage activation and the secretion of gamma-interferon (IFN-γ), IL-2, and TNF-α, which can exacerbate atherosclerosis and associated inflammation." (PMID 40242436, 2025). "Beyond that, increased inflammatory mediators, such as NF-κB, IL-6, and TNF-α (related to ROS and inflammation excess), increase the risk of atherosclerosis injuries and damage in the liver vessels." (PMID 39458995, 2024). "Increased levels of TNF-α and IL-6 are identified as risk factors for the development of atherosclerosis and CVD." (PMID 39742290, 2024). "The upregulated genes in the keloid C1 mast cell subcluster, the major subcluster of mast cells, were associated with lipids and atherosclerosis, the TNF signaling pathway, and the IL-17 signaling pathway." (PMID 39872534, 2024). "TNF-a has been associated with the development and advancement of atherosclerosis and its related outcomes, such as acute coronary syndrome." (PMID 38807048, 2024). "fInflammation is a basic pathogenic factor during the development of atherosclerosis, and TNF-α is a key pro-inflammatory cytokine involved in the inflammatory reaction and plays a pivotal role in the formation and development of atherosclerotic plaque." (PMID 38961881, 2024). "The main signaling pathways implicated are Lipid and atherosclerosis, TNF, IL-17, Toll-like receptor and C-type lectin receptor signaling pathway." (PMID 39015338, 2024). "Metabolically, the cytokines secreted by visceral fat, including leptin, adiponectin, and TNF-α, can incite inflammatory responses and cause endothelial dysfunction, thereby facilitating atherosclerosis and heightening the risk of CVD." (PMID 39458542, 2024). "After excluding systemically treated patients, LogIL-17A and Log TNF-α were associated with the likelihood of atherosclerosis (p < 0.05)." (PMID 39104857, 2024). "It has been reported that abnormally high serum levels of TNF-α – which is a major proinflammatory cytokine – are associated with an increased incidence of atherosclerosis and hypertension." (PMID 39876967, 2024).
atherosclerosis (continued). "Tumor necrosis factor-alpha (TNF-α) is another key cytokine involved in systemic inflammation and has been implicated in the pathogenesis of heart failure and atherosclerosis." (PMID 39057626, 2024). "In a mouse model of atherosclerosis induced by a high-fat diet, oral administration of GRb1 was found to suppress levels of inflammatory factors such as IL-1β, IL-6, and TNF-α in serum, attenuating apoptosis associated with inflammatory activity." (PMID 39339421, 2024). "On the other hand, oxidative stress can result in the production of inflammatory mediators, including interleukin-6 and tumor necrosis factor-alpha, and affect the ovary and endothelium causing anovulation and premature atherosclerosis in PCOS." (PMID 38997723, 2024). "Elevated TNF-α levels are associated with HF and atherosclerosis, reflecting the underlying inflammatory processes that contribute to cardiovascular disease." (PMID 39273041, 2024). "The Kyoto Encyclopedia of Genes and Genomes (KEGG) analysis of the pivotal DE-LAGs demonstrated associations with lipid and atherosclerosis, as well as the IL-17 and TNF signaling pathways." (PMID 38637111, 2024). "KEGG pathway analysis highlighted three significant pathways: the TNF signaling pathway, NF-κB signaling pathway, and the lipid and atherosclerosis pathway—all of which are closely associated with inflammation." (PMID 38962312, 2024). "The protein encoded by the PRTN3 gene is one of the main components of neutrophils and is involved in the activation and processing of pro-inflammatory cytokines associated with atherosclerosis, such as IL-1β, TNF-α, and MCP-1." (PMID 39609876, 2024). "Prospective Cohort Studies: There are three such studies, all indicating that TNF-α inhibitors were associated with improved atherosclerosis metrics." (PMID 39739136, 2024). "The findings revealed an association between the TNF signaling pathway, NF-kappa B signaling pathway, lipid and atherosclerosis, toll-like receptor signaling pathway, apoptosis, neutrophil extracellular trap formation." (PMID 38166912, 2024). "These cells produced higher levels of inflammatory molecules associated with atherosclerosis, including TNF-α, ROS, and matrix metalloproteinases, in PLWH compared with cells in PWoH." (PMID 39000373, 2024). "The dysregulation of TNF-α is associated with a variety of pathological conditions, such as infection, autoimmune diseases, cancer, atherosclerosis, Alzheimer’s disease, inflammatory bowel disease, and intervertebral disc degeneration." (PMID 39203919, 2024). "TNF-alpha has been reported to promote the atherosclerosis in mice, and that the activated pathways of TNF-alpha signal transduction have possible roles in induction of atherosclerosis, an important cause of stroke." (PMID 37240845, 2023). "Pathway enrichment analysis indicated that the targets of SC were enriched in diverse pathways implicated in OP pathology, such as AGE-RAGE, lipid and atherosclerosis, IL-17, Estrogen, and TNF signaling pathway." (PMID 37089711, 2023). "Heart disease, atherosclerosis, and hypertension are all associated with increased pro-inflammatory cytokines, such as tumor necrosis factor-alpha (TNF-α), interleukin (IL)-1β, IL-6, and interferon-gamma (IFN-γ)." (PMID 37238657, 2023). "TNF-α is known for its proinflammatory activity, and dysregulation of TNF-α is associated with a variety of pathological conditions, such as infections, autoimmune diseases, atherosclerosis, and inflammatory bowel disease." (PMID 36825443, 2023). "After Ang-II infusion, expression of tumor necrosis factor (TNF)-α-converting enzyme (TACE) increases in atherosclerosis and left ventricle, and ADAM17 polymorphism is associated with cardiovascular mortality." (PMID 37374349, 2023). "TNF-α inhibitors: TNF-α promotes numerous inflammatory responses associated with atherosclerosis, including induction of vascular adhesion and monocyte/macrophage proliferation." (PMID 37763669, 2023).
atherosclerosis (continued). "The lack of MCP-1, MCP-1 receptor CCR2 inhibition, IL-1β deficiency, and TNF-α inhibition have been shown to decrease atherosclerosis formation." (PMID 37107335, 2023). "Patients with type 2 diabetes, overweight and atherosclerosis have increased levels of inflammatory cytokines, such as tumor necrosis factor alpha (TNF-α) and interleucin-6 (IL-6), and LPS, which is caused by low-grade endotoxaemia." (PMID 36915164, 2023). "The TEBVs were perfused with labeled monocytes during TNF-α and eLDL treatment to evaluate adhesion of these monocytes to the cell wall, a hallmark of early stage atherosclerosis." (PMID 37854060, 2023). "These genes were primarily associated with the TNF signaling pathway, the IL-17 signaling pathway, lipid and atherosclerosis pathways, the AGE − RAGE signaling pathway in those with diabetic complications, and the MAPK signaling pathway." (PMID 37293297, 2023). "What's more, in a dose-dependent manner, naringin appears to reduce the risk of atherosclerosis by inhibiting the adhesion of THP-1 monocytes to TNF-α-stimulated HUVECs." (PMID 36823573, 2023). "TNF and IL-6 are two proinflammatory cytokines associated with atherosclerosis, plaque development, and increased cardiovascular risk." (PMID 37664830, 2023). "HFD-induced TNF-α secretion in the myocardial tissue can stimulate the adhesion of monocytes to endothelial cells and cause atherosclerosis." (PMID 37764856, 2023). "TNF-alpha levels in the blood have been linked to atherosclerosis of coronary artery risk factors such as dyslipidemia, overweight, and inflammation." (PMID 36622512, 2023). "The pro‐inflammatory cytokines, including IL‐1β, Interleukin 6 (IL‐6) and tumour necrosis factor‐alpha (TNF‐α), have been regarded as the risk factors in atherosclerosis." (PMID 37905351, 2023). "B2 B cells promote the development/progression of atherosclerosis in hyperlipidemic mice by secreting inflammatory cytokines such as TNF-α and pathogenic antibodies." (PMID 36836225, 2023). "Across studies TNF-α and IL-1β are correlated to the reduction in atherosclerosis-associated inflammation." (PMID 36904211, 2023). "For instance, miR-467b has been implicated in the regulation of atherosclerosis and secretion of the proinflammatory cytokines IL-6, IL-1β, and TNF, which are also knowingly dysregulated in CCC." (PMID 36972298, 2023). "A large number of studies indicate a decrease in the rate of development of atherosclerosis with a deficiency of TNF-α." (PMID 37047399, 2023). "High sensitivity C-reactive protein is currently used as a risk biomarker in overt atherosclerosis, but also TNF-α seems to be involved in the systemic inflammatory response, leading to vascular dysfunction and atherosclerotic plaque instability." (PMID 37189813, 2023). "Inflammation is implicated in atherosclerosis along with the accumulation of leukocytes and inflammatory mediators such as interleukin (IL)-1β and IL-6, and TNF-α increases the levels of inflammatory factors in VSMCs." (PMID 36060429, 2022). "Hyperlipidemia is a major risk factor for atherosclerosis, and the levels of pro-inflammatory cytokines, such as TNF-α, IL-1β, and IL-6, are usually increased and play a vital role during the early progression of atherosclerotic plaques." (PMID 36500975, 2022). "Since tumor necrosis factor-alpha inhibitors (TNFi) inhibit the inflammatory cascade, they also play an essential role in dampening the progression of atherosclerosis and altering the risk of cardiovascular outcomes in RA." (PMID 35915691, 2022). "Pro-inflammatory cytokines, such as IL-1β, IL-6, and TNF-α play important roles in atherosclerosis progression and are associated with adipokines." (PMID 35566578, 2022). "Hyperleptinemia is linked to the progression of atherosclerosis by promoting inflammation through the release of proinflammatory cytokines such as IL-6, TNF-α, IL-17, and other cytokines." (PMID 35282557, 2022).
atherosclerosis (continued). "Our KEGG study demonstrated that lipids and atherosclerosis, the IL-17 signalling pathway, and the TNF signalling pathway are all linked to EU's therapeutic mechanism for the treatment of AS." (PMID 36267087, 2022). "CD40L, TNF-α, and IL-1β have been extensively evaluated in experimental atherosclerosis and the development of underlying cardiometabolic risk factors." (PMID 35252400, 2022). "Taken together, it seems that somatic TNFα deficiency has a greater impact on atherosclerosis development as it decreases endothelial adhesion molecule expression as well as foam cell formation compared to hematopoietic TNF-α deficiency." (PMID 35600479, 2022). "Postprandial hyperlipidemia (PPHL) in RA patients was associated with subclinical atherosclerosis (p=0.037), TNF-α (p=0.048), and high-sensitivity C-reactive protein (p=0.027)." (PMID 36249997, 2022). "Elevated levels of IFN-γ and TNF-α, increased T-cell chelators and adhesion molecules, and progressive loss of endothelial barrier integrity are observed during atherosclerosis formation, both in vivo and in vitro experiments." (PMID 35514987, 2022). "Inflammation is a fundamental pathogenic factor in the development of atherosclerosis, and both periostin and TNF-α are important proinflammatory cytokines involved in the inflammatory response that can regulate each other to promote an inflammatory response." (PMID 36127647, 2022). "It is roughly understood that inflammation linked with the hyperactivation of cytokines, such as IL-1β, IL-6, IL-10, and TNF-α causes pathogenesis of coronary heart disease and atherosclerosis." (PMID 36289895, 2022). "The TNF-α cytokine was previously shown to a play critical role in atherosclerosis development while TNF-α deficiency has been associated with decreased plaque inflammation." (PMID 35900662, 2022). "Elevated levels of CRP, IL-1β, IL-6 and TNF-α in patients with chronic inflammatory diseases stimulate the initiation and accelerate the progression of atherosclerosis, increasing markedly risk of CVD events." (PMID 36297390, 2022). "The levels of inflammatory markers (IL-6, C-reactive protein, and TNF-alpha) are determined along with antibody titers to three latent viruses associated with atherosclerosis." (PMID 35911274, 2022). "TNF-α is a pro-inflammation cytokine that plays an important role in atherosclerosis, which underlies most CHD events." (PMID 34627379, 2021). "The cytokine TNF-α is very important in pathogenesis of RA by reducing inflammation and, subsequently, the risk of atherosclerosis." (PMID 33259776, 2021). "The biological pathway was significantly activated in the TNF signaling pathway, fluid shear stress, atherosclerosis, and Kaposi’s sarcoma-associated herpesvirus infection." (PMID 34163322, 2021). "Inflammatory cytokines, such as tumor necrosis factor-α and interleukin-6, can enhance the differentiation of the macrophage and are responsible for the interaction between bone loss and atherosclerosis in RA patients." (PMID 34641970, 2021). "Some reports stated that various extracts from PE cause inhibition of the production of TNF-α, IL-1β, and IL-6 in atherosclerosis or neuronal cellular model." (PMID 34712342, 2021). "Atherosclerosis associated inflammation enhances inflammatory factor accumulation, including tumor necrosis factor-α (TNF-α), which promotes the expression of miRNA-155 in ECs-derived EVs." (PMID 34692785, 2021). "Tumor necrosis factor-α (TNF-α) is an important cytokine associated with atherosclerosis progression." (PMID 33767629, 2021). "Infiltrated leukocytes can be differentiated into macrophages and release tumor necrosis factor-α (TNF-α) and consequently crucial risk factor for atherosclerosis because inflammation is closely regulated by signaling processes in vessel." (PMID 34961267, 2021).
atherosclerosis (continued). "Enrichment analysis revealed that genes in the blue module were primarily enriched in atherosclerosis-associated functions and pathways, including neutrophil activation, neutrophil mediated immune response and TNF signaling pathway." (PMID 34688276, 2021). "Systemic inflammation and pro-inflammatory cytokines including tumor necrosis factor α (TNF-α) are involved in the pathogenesis of arthritis-associated secondary atherosclerosis and CV disease." (PMID 35155468, 2021). "In agreement, bone marrow derived macrophages from an ACE2-deficient, atherosclerosis mouse model exhibited a higher baseline level of pro-inflammatory cytokines (e.g., TNFα and IL-6) and hyper-responsiveness to LPS and TNF-α stimulation." (PMID 34163462, 2021). "In animal models, we demonstrate that LXN deficiency inhibits VEGF and TNF‐α‐induced vascular permeability, as well as significantly improves vasodilation and atherosclerosis in mice fed with high‐fat diet." (PMID 34085389, 2021). "Accordingly, atherosclerosis-prone animals deficient for TNFα (double ApoE/TNFα KO) express lower amounts of lipoprotein scavenger receptors and show less fatty streak formation, as compared to ApoE KO littermates when 6 months of age." (PMID 33770265, 2021). "Secretion of inflammatory adipokine suggests the role of EAT that can cause atherosclerosis; the increase in the level of TNF-α and MCP-1 is correlated with the generation of atherosclerosis, where the TNF-α increases the manifestation of adhesion molecule." (PMID 33809392, 2021). "Since TNF-α is a pro-inflammatory cytokine, it was expected that the deficiency of TNF-α would protect against atherosclerosis; however, the size of aortic atherosclerosis lesion in TNF-α-null mice was 2.3 times larger than that in wild-type mice." (PMID 34071276, 2021). "Experimental and observational studies have linked TNF signaling with the pathogenesis of atherosclerosis." (PMID 34988343, 2021). "Basically, TWEAK is a secreted pro-inflammatory multifunctional ligand of the TNF super-family, being involved in chronic inflammation and in the development of clinically-relevant associated processes, such as atherosclerosis." (PMID 34768497, 2021). "This cytokine has been shown to be responsible for initiating the atherosclerosis process in rodents with diminished activity of apolipoprotein E. The association between adhesion molecules, TNF-α and IL-6 is common in ESRD, promoting atherosclerosis." (PMID 34441451, 2021). "At the same time, interleukin 6 (IL-6) and tumor necrosis factor-alpha (TNF-α) increase and are linked to the development of cardiovascular disease, atherosclerosis, and others." (PMID 34072421, 2021). "Recently, it has been revealed that many inflammatory markers, such as CRP, platelet/lymphocyte ratio (PLR) and neutrophil/lymphocyte ratio (NLR), WBC, TNF-α, and cytokines can be independent risk factors for atherosclerosis." (PMID 33134969, 2020). "TNFα produced from B cells is implicated in atherosclerosis, so perhaps B cell derived TNFα is targeted." (PMID 32671098, 2020). "Chronic inflammation and overexpression of TNF-α is associated with the pathophysiology of pulmonary arterial hypertension and atherosclerosis." (PMID 32576665, 2020). "Summarizing, in the light of published clinical data, anti-TNF-α treatment seems to reduce the risk of cardiovascular episodes mainly by inhibiting systemic inflammation and thereby suppressing the development of atherosclerosis and ischemic events." (PMID 33053859, 2020). "Increased TNF-α levels have been associated with atherosclerosis and coronary heart disease post-infection with Chlamydia pneumoniae (C. pneumoniae)." (PMID 32326284, 2020). "The potentially causal role of TNF in heart failure, atherosclerosis in a range of vascular beds and other cardiovascular diseases therefore need to be investigated." (PMID 32805626, 2020).